IL10 (interleukin 10)
Diseases named in the same sentence as IL10 in open-access papers (continued):
Sharing a sentence is not in itself a finding about the gene and the disease.
tumor (continued). "IL-35 converts B cells and T cells into IL-10 and IL-35 producing Bregs and Tregs, promoting tumor growth and metastasis." (PMID 39840050, 2024). "In the tumor microenvironment, IL-10 and IL-35, primarily secreted by different Tregs subsets, are instrumental in modulating immune responses." (PMID 38500876, 2024). "Interleukin-10 (IL-10) is a pleiotropic cytokine with immunoregulatory effects in tumor microenvironment." (PMID 38279997, 2024). "It was proven that the presence of PD-L1 on tumour cells and APCs leads to the induction of T cell apoptosis, their anergy or exhaustion, elevated IL-10 production, abnormalities in the proper function of DCs, and the elevated differentiation of Tregs." (PMID 38892453, 2024). "The TME contains chemicals such tumor antigens, IL-2, IL-10, TGF-β, and other soluble molecules that stimulate the T-cell receptor (TCR) and enhance the transformation of naive CD4+ T-cells into iTregs." (PMID 38509593, 2024). "IL-10 plays a complex role in the tumor–immune cell intrinsic interactions and has been shown to be involved in the development and progression of several cancers, such as OC." (PMID 39199610, 2024). "Nonetheless, factors like IL-6, TGF-β, and IL-10, secreted by tumor cells, perpetuate chronic inflammation, stimulating immunosuppressive myeloid-derived suppressor cells, macrophages, and neutrophils." (PMID 39664377, 2024). "These TAMs produce factors such as cytokines (TGF-β and IL-10), growth factors and chemokines, that inhibit the activity of cytotoxic T cells and facilitate tumor progression and metastasis." (PMID 39483536, 2024). "IL-10, a pleiotropic immunoregulatory cytokine secreted by various cells, including lymphoid, myeloid, and tumor cells, mediates immune homeostasis and tolerance while also promoting immunosuppression." (PMID 39118076, 2024). "Certain tumor cells were found to produce IL-10, thereby upregulating the expression of HLA-G, which, in turn, induced immune cells to produce IL-10, IL-4 and IL-3." (PMID 38279997, 2024). "One notable mechanism is the promotion of cytokines such as interleukin-10 (IL-10), an anti-inflammatory cytokine from innate and adaptive immune cells, facilitating tumor tolerance." (PMID 39118076, 2024). "IL-10 can stimulate cytotoxicity of tumor-resident CD8+ T cells but reduces CD8+ cell capacity to control pathogen burdens in chronic viral infections." (PMID 39682467, 2024). "IL10 can suppress the activity of cytotoxic T cells and natural killer (NK) cells, which are critical for tumor surveillance and elimination." (PMID 39050251, 2024). "TCR-engineered CD8+ T cells secreted IL-2, IL-4, IL-6, and IL-10 when cocultured with KRASG12V tumor cell lines." (PMID 39287991, 2024). "Overexpression of TGFβ and IL10R2 enhances IL22/STAT3 signaling in colitis-associated colorectal carcinogenesis, and Wnt5a-mediated IL10 secretion from macrophages ultimately promotes tumor growth and metastasis." (PMID 38844562, 2024). "IL-4 upregulates other tumor microenvironmental cytokines including IL-10 which induce immunosuppressive conditions and thus peripheral tolerance of tumor-infiltrating immune cells." (PMID 39057050, 2024). "In conclusion, we observed an additive effect of treatment with 223Ra on immune function and found that IL-10 secretion at baseline predicted tumor burden at month 6 after treatment." (PMID 38473247, 2024). "THBS1, a matricellular protein, is strongly expressed during inflammation and plays roles in inducing macrophage IL-10 production, inhibiting angiogenesis, modulating immune responses, and affecting tumor development." (PMID 39453208, 2024). "At the same time, MDSCs induce the transformation of tumor-specific T cells into Tregs via mechanisms that are dependent on IL-10 and TGF-β." (PMID 38404689, 2024). "In many instances, tumor-infiltrating B cells undergo transformation into regulatory B (Breg) cells and secrete cytokines such as IL-10 and TGF-β, which promote tumor progression." (PMID 39456702, 2024).
tumor (continued). "An increase in IL-10+ Bregs have been documented in the peripheral blood and tumours of patients with malignancy, including breast, gastric, and oesophageal cancers." (PMID 39346706, 2024). "Restoration of the intestinal microbiome and its metabolic functions inhibit tumor growth and reverse the immunosuppression due to increased PD-L1 and IL-10 levels in PBMCs and tumor cells of GC patients." (PMID 38197259, 2024). "Tumor-derived factors (i.e., IL-6, IL-10, IL-1β, PGE2, VEGF, GM-CSF, M-CSF, and IFN-γ) are implicated in the induction of MDSCs." (PMID 39272914, 2024). "In contrast, an in vivo study suggested that blood monocytes promote tumor growth by differentiating into tolerogenic dendritic cells (DCs) that produce interleukin-10 (IL-10) and potently induce regulatory T cell responses." (PMID 39628488, 2024). "Tumor growth is driven directly by M2-like macrophages through the release of IL-1β, IL-6, IL-10, CCL18 and CCL20, as well as indirectly through the suppression of cytotoxic cell populations, including CD8+ T cells and NK cells." (PMID 38957393, 2024). "The TME often contains a high concentration of immunosuppressive cells, such as regulatory T cells (Tregs), myeloid-derived suppressor cells (MDSCs), and tumor-associated macrophages (TAMs), which secrete inhibitory cytokines (e.g., TGF-β and IL-10)." (PMID 39802949, 2024). "Meanwhile, decreased suppressive cytokine IL10 and increased tumor-killing cytokine IFNγ expression were detected in IFITM3-deficient TI-Treg cells." (PMID 38167862, 2024). "An IL-10 blockade antibody drives accumulation of TILs, release of granzyme B, and tumor cell necrosis in an in vitro human CRC culture system." (PMID 38918278, 2024). "Future experimental work is necessary to dissect the intricate signaling pathways through which IL-10 influences B cell differentiation and the broader implications for tumor immune evasion." (PMID 39896813, 2024). "But, for the IAA injection alone, the immune cells were rare in the U14-grafted tumor site, and it was difficult to induce IL-10 and IFN-γ production." (PMID 38540186, 2024). "Regulatory B cells (Bregs) promote tumor immune escape by secreting cytokines such as IL-10, TGF-β1, IL-35, PD-L1 and so on." (PMID 38953025, 2024). "TAMs can also suppress T cell cytotoxicity by secreting IL-10, promote regulatory T cells, leading to immune evasion and tumor proliferation." (PMID 38650924, 2024). "pDCs exposed to tumor tissue stimulate Tregs to increase IL-10 production by up-regulating the expression of ICOS-L." (PMID 38927922, 2024). "The tumor burden correlated negatively with IL-10 secretion at baseline, e.g., after stimulation with tetanus antigen (p < 0.0001, r = −0.82)." (PMID 38473247, 2024). "TAM secretion of IL-10 impedes dendritic cells from activating anti-tumor T cell responses, while TGF-β1 production by TAMs fosters the survival of regulatory T cells, further exacerbating the immunosuppressive environment." (PMID 39410029, 2024). "The anti-inflammatory functions of IL-10 initially fueled the idea that it acts as a suppressor of immune responses in the tumor context, thereby favoring tumor development." (PMID 39281678, 2024). "Several cytokines, including TNF-α, IL-10, IL-17, and IL-1β, have been shown to play an important role in the tumor inflammatory environment or tumor immune response." (PMID 38734702, 2024). "Environmental conditions in the tumor can further stimulate M2 polarization: production of IL-10, TGFβ, and MCSF is increased under hypoxic conditions, and the acidosis caused by high rates of anerobic glycolysis in tumor cells can enhance M2 differentiation." (PMID 38254801, 2024). "Tregs prevent an efficient immune response against tumor cells and produce immunosuppressive cytokines such as IL-10 and TGF-β suppressing the activity of effector T cells (such as CD8+ T cells) and NK cells." (PMID 39766138, 2024).
tumor (continued). "Malignant cells hinder the proliferation of cytotoxic T lymphocytes (CTLs) within the tumor by generating immunosuppressive cytokines like interleukin (IL)-10, vascular endothelial growth factor (VEGF), and transforming growth factor beta (TGF-β)." (PMID 39057108, 2024). "The results demonstrated that lymphocytes cultured with oncogenes-transfected tumor cells promoted an increase in the release of the cytokines IL-2, IL-4, IL-10, and TNF-α, with differences in the releases from different transfected oncoproteins." (PMID 39599846, 2024). "Contrary to the notion that IL-10 promotes immunosuppressive TMEs, it activates tumor-resident CD8+ T-lymphocytes." (PMID 39421736, 2024). "Serum analysis revealed that both IgG4 (P<0.01, **) and IL-10 (P<0.0001, ****) were significantly elevated and positively correlated in tumor patients compared to controls (P<0.01, **)." (PMID 39896813, 2024). "For example, several cytokines and chemokines generally considered to be predominantly toxic or immunosuppressive (IL-6, IL-8 and IL-10) have been shown to stimulate anti-tumor immune responses in certain settings." (PMID 39606250, 2024). "By employing the MCODE plugin in Cytoscape, we identified key sub-networks within the PPI network, which included genes such as IL-10, CD3E, MET, and others that were associated with anti-tumor immune response." (PMID 38327746, 2024). "At the same time, in the tumor tissue of the SH mice, the expression levels of anti-inflammatory cytokines Il10 and Tgfb were statistically significantly higher than in the TH mice." (PMID 39063041, 2024). "For example, in B cells, IL-10 promotes proliferation, stimulates immunoglobulin secretion and isotype switching, and enhances tumor-killing capabilities." (PMID 39726592, 2024). "This dual role makes IL-10 a double-edged sword: it can suppress anti-tumor immune responses and promote tumor growth, but it also holds potential as a treatment for autoimmune and inflammatory diseases." (PMID 39118076, 2024). "NKint, NK1A and NK1B cells seemed to be more susceptible to IL-10 and PGE2, which are signals that can dampen immune responses, in particular in the tumor microenvironment." (PMID 38956378, 2024). "Significant differences in IL-10 secretion were observed between the Hc-treated and the untreated control groups, as the high level of this tolerogenic cytokine suggests tumor progression." (PMID 38786612, 2024). "The CBM588-induced ability to secrete Interleukin-10 of lamina propria mononuclear cells was heightened in tumor bearers when compared with cancer-free mice." (PMID 38385162, 2024). "It is evident from these studies that the tumor-promoting effect of B cells is mainly attributed to the regulation of B cells that secrete immunosuppressive cytokines like IL-10." (PMID 38791916, 2024). "Co-culture of Bregs with tumour-infiltrating follicular cytotoxic CD8+ T (Tfc) cells increased Tfc expression of IL-10 and reduced Tfc expression of pro-inflammatory IFN‐γ, TNF, and IL-2 in NSCLC patients." (PMID 39346706, 2024). "Further database analysis (TIMER2.0) showed that PDCD1 gene expression was positively correlated with the levels of immunosuppressive genes (CD274, PDCD1LG2, TGFB1, and IL10) in most human tumor types." (PMID 38441961, 2024). "HCC tumour MSDC-derived IL-10 suppressed the ability of dendritic cells to produce IL-12 and stimulate T cells." (PMID 38464388, 2024). "These PD-L1+TAMs, activated by tumor-derived IL-10, have been proposed to mediate CD8+ T cell dysfunction through the PD-1/PD-L1 interaction." (PMID 38957393, 2024).
tumor (continued). "While tumor immunity is mainly governed by Th1-mediated cellular responses, we observed that preexisting higher levels of IL-5, IL-4, and IL-10 were also correlated with better clinical responses." (PMID 38231411, 2024). "The multifaceted role of IL-10 in cancer is well-documented, encompassing both tumor-promoting and tumor-suppressive functions." (PMID 39118076, 2024). "In later stages, TAMs exhibit M2-like characteristics, with reduced IL-12 and elevated IL-10 levels, impairing their anti-tumor capabilities." (PMID 39575419, 2024). "These cells release immunosuppressive factors such as TGF-β and IL-10, which can inhibit the activity of cytotoxic T cells, thus creating a more favorable growth environment for tumor cells." (PMID 38646440, 2024). "These immunosuppressive cells release cytokines such as transforming growth factor-beta (TGFβ) and interleukin-10 (IL-10), which diminish the anti-tumor effects of CAR-T cells upon infusion." (PMID 38953982, 2024). "The complexity of IL-10’s function is highlighted by its paradoxical roles in cancer, where it can exhibit both pro- and antitumor effects within the tumor microenvironment." (PMID 38672104, 2024). "Persistent IL-10 and TGF-β signaling, on the other hand, introduce selective pressure to overcome the tumor-suppressive effects of TGF-β or IL-10." (PMID 38543305, 2024). "On the other hand, AgNPs-G treatment significantly decreased the levels of IL-2, IL-4, and IL-10 in tumor tissue compared to the control group." (PMID 39126001, 2024). "For example, MCs release FGF-2, NGF, PDGF, VEGF, IL-8, and IL-10, which promote the expansion of tumor cells." (PMID 38233752, 2024). "TAMs and Tregs overexpress IL-10, which down-regulates the content of IL-12 released by DCs, thereby limiting the stimulation of the tumor immune response." (PMID 38590651, 2024). "In our study, we evaluated the concentration of circulating inflammatory-mediated cytokines (IL-10, IL-6, and IL-1ß) in all groups at different time intervals before and after tumor resection." (PMID 38662232, 2024). "SAADKO tumor-bearing mice displayed lower concentrations of IL-1β (p = 0.030), IL-6 (p = 0.003), and IL-10 (p = 0.014) compared to WT tumor-bearing mice." (PMID 39336082, 2024). "The role of IL-10 in cancer is complex, as it can exhibit both anti-tumor and pro-tumor effects depending on the context." (PMID 39769247, 2024). "It is capable of activating VEGF synthesis and thus influences tumor vascularization and angiogenesis, as well as induces IL-10 production both locally and systemically." (PMID 39063041, 2024). "It has been shown that sustained elevated serum concentrations of IL-10, as achieved by PEGylation, can induce enhanced cytotoxicity and expansion of tumor-specific CD8+ T cells in animal studies." (PMID 39796154, 2024). "IL-10 can suppress myeloid and chronic inflammatory T cell responses and expand tumor specific CD8+ T cells." (PMID 38685033, 2024). "Anti-tumor macrophages (M1) can polarize into pro-tumor macrophages (M2) via IL-4, IL-10, and IL-13." (PMID 39125923, 2024). "In contrast, M2 macrophages generate IL-13, IL-10, and other factors that foster tumor development and enhance the invasive capabilities of tumor cells." (PMID 39290709, 2024). "In contrast, M2 macrophages, induced by IL-4, IL-10, IL-13 or glucocorticoids, secrete anti-inflammatory cytokines like IL-10 and IL-1β, and they play a role in promoting angiogenesis, tissue remodeling, injury repair, tumor initiation, and progression." (PMID 39877377, 2024). "Blocking IL-10 signaling also presents an immunotherapy strategy due to IL-10’s tumor immunosuppressive effect." (PMID 38279997, 2024). "Tumor-induced dendritic cells (DCs) can also directly inhibit T-cell proliferation by secreting immunosuppressive cytokines such as IL-10 or TGF-β." (PMID 38725629, 2024).
tumor (continued). "Treg cells, recipients of miRNA-214, present reduced PTEN levels and secrete higher amounts of IL-10, which contributes to the promotion of tumor growth." (PMID 39195233, 2024). "The release of CCL4 aids in tumor invasion, IL10 plays a role in immunosuppression, and THBD contributes to enhanced resistance to TMZ." (PMID 38832259, 2024). "Exosomes isolated from tumor cells were found to facilitate the generation and expansion of Tregs, allowing the immune escape of tumor cells through the release of immunosuppressive cytokines, such as IL-10 and TGF-β1." (PMID 38391950, 2024). "The proliferation of Treg cells is further fueled by immunosuppressive cytokines like TGF-β and IL-10, produced by both tumor cells and immune cells within the TME." (PMID 39409893, 2024). "Tumor-infiltrating M2 TAMs directly promote cancer growth and metastasis by secreting regulatory cytokines, including IL-10 and ARG-1, whereas M1 TAMs have the opposite effects." (PMID 39020380, 2024). "Preclinical studies show that targeting IL-10 and PD-L1, combined with macrophage reprogramming agents, can reduce tumor burden and enhance treatment efficacy." (PMID 39539544, 2024). "MDSCs are induced at the affected sites by tumor cells and contribute to tumor growth by directly suppressing immune cells such as cytotoxic T cells via their production of cytokines including IL-10 and TGF-β, or indirectly by inducing T-regs." (PMID 38566990, 2024). "IL-10 also has potent antiangiogenic activity and can inhibit tumor growth and metastasis formation." (PMID 39273323, 2024). "These exosomes promote the overexpression of PD-L1 in immature myelo-monocytic precursors and CD206+ macrophages, stimulating macrophages to produce arginase-1 and IL-10 to suppress anti-tumor immune responses and thereby accelerate tumor growth." (PMID 38779660, 2024). "IL-10 is downregulated far before tumor volume begins to grow, likely to allow for less immunosuppression and more angiogenesis at the site to enable tumor growth." (PMID 39451257, 2024). "High amounts of TGF-β, IL-10 and IL-32 are produced by Tregs, which further suppress the anti-tumor inflammatory response and trigger M2 macrophages to generate more cytokines and chemokines, allowing for the recruitment of more Tregs." (PMID 38935134, 2024). "IFN-I can prompt Tregs to secrete IL-10 in the tumor microenvironment (TME), enhancing their suppressive capability." (PMID 38672681, 2024). "When activated by their environment, Tregs can dampen the anti-tumor immune response by releasing inhibitory cytokines like IL-10, IL-35, and TGF-β; thus, fostering tumorigenesis." (PMID 38903506, 2024). "Anti‐inflammatory IL‐10 is associated with poor prognosis, and in animal models, inhibiting IL‐10 signaling hinders tumor growth." (PMID 38600057, 2024). "In support of this notion, suppression of IL-10 expression has been shown to enhance anti-tumor T cell immunity in combination with PD-L1 blockade in a preclinical mouse model." (PMID 38360867, 2024). "IL-10 is one of the important cytokines secreted by macrophages, which can promote tumor progression." (PMID 38970064, 2024). "This IL-10-mediated T-cell dysfunction ultimately promotes tumor cell growth and suppresses the immune response against the tumor." (PMID 39156969, 2024). "Influence of this tumor conditioning media (TCM) resulted in upsurged levels of IL-10 alongside abated IL-12p35 production." (PMID 38649988, 2024). "Depleting IL-10+ B cells can diminish pro-tumour immune responses by enhancing cytolytic abilities of splenic cytotoxic T lymphocyte, and B cells." (PMID 39346706, 2024). "Other predicted mechanisms include JAK/STAT3-mediated production of IL-10 and TGFβ, promotion of switching from M1 to M2 macrophages, and suppression of anti-tumor immunity via the CCL2-CCR2-M2 macrophage axis." (PMID 38785789, 2024).